CHEK2 (checkpoint kinase 2)
Diseases named in the same sentence as CHEK2 in open-access papers (continued):
Sharing a sentence is not in itself a finding about the gene and the disease.
cancer (continued). "Additionally, in 23 PDAC patients (7.7%) 25 PV were found in other cancer predisposition genes for which a clear association with PDAC has not (yet) been established; one third of them in CHEK2." (PMID 34503238, 2021). "However, given that we are testing a pediatric population, many of the patients’ first-degree relatives are relatively young at the time of diagnosis and may not have developed a canonical CHEK2-related cancer at the time of testing." (PMID 36980535, 2023). "Additionally, clinical information unrelated to cancers and precancerous findings were not documented on the TRF, and this study could not identify an association between biallelic CHEK2 PVs and other phenotypes." (PMID 31993860, 2020). "During the last three years also deep sequencing data on solid cancer unveiled unexpected germline gene aberrations in neuroendocrine neoplasia (e.g., MUTYH, CHEK2, and BRCA2 genes in pancreas NEN) together with a substantial absence of known cancer drivers." (PMID 32869113, 2021). "Among them, the most frequent were reported in PALB2 and CHEK2, further confirming their involvement in some non-BRCA cancers." (PMID 31936873, 2020). "CHEK2 is not on the ACMG list, but the NCCN recommends increased cancer screening starting at younger ages for patients with CHEK2 variants." (PMID 30487145, 2018).
tumor (482 papers, 2002 to 2026). "The discovery of the c.1100delC truncating mutation provided evidence that CHEK2 functions as a tumor suppressor, a role that remains widely supported in literature." (PMID 40492861, 2025). "It is important to note that the CHEK2 variant data of MUM were analyzed from tumor tissue sections, and pathogenic somatic mutations in GNA11 or GNAQ, along with BAP1, were detected alongside the CHEK2 variants in the UM metastatic tissues." (PMID 40283643, 2025). "The CHEK2 (Checkpoint kinase 2) gene that encodes the protein CHK2, a serine-threonine kinase, is a cell cycle checkpoint regulator that acts as a tumor suppressor." (PMID 40283643, 2025). "CHEK2 encodes a protein that functions as a regulator of the cell cycle as well as a tumor suppressor." (PMID 39901230, 2025). "The serine/threonine kinase CHK2 (checkpoint kinase 2) is a key mediator of the DNA damage response and tumor suppressor and has been implicated in promoting cell cycle arrest, apoptosis, and DNA repair." (PMID 40990019, 2025). "In CHEK2 deficient tumor lines treated with PD-1 inhibitor, tumors showed significant regression in volume and increased CD8+ T-cell infiltration." (PMID 40492861, 2025). "Subsequently, we identified CHEK2 variants in seven additional MUM cases from the Caris Life Sciences tumor database between 2016 and 2023." (PMID 40283643, 2025). "CHEK2 p.(Arg474 Cys) likely pathogenic variant was observed only in the well-differentiated component of the tumor." (PMID 40448797, 2025). "Hazard ratios (HRs) and 95 % confidence intervals (CI) for the association of CHEK2-status with prognosis were estimated via delayed entry Cox regression models, adjusted for age and year of diagnosis, tumor size, nodal status, and primary treatment regimens." (PMID 41314031, 2025). "Known founder mutations were identified in tumor profiling reports of seven unique cases (8.4%; 7/83), including CHEK2 (I157T, n = 1), HOXB13 (G84E, n = 2) and MUTYH (G368D, n = 2 and Y151C, n = 2)." (PMID 39885482, 2025). "CHEK2 is a tumor suppressor gene that encodes the serine/threonine protein kinase CHK2, which is a key mediator of the DNA damage checkpoint that responds to DNA double-strand breaks, playing a crucial role in the maintenance of genomic integrity." (PMID 38367672, 2024). "CHEK2 is a tumor suppressor gene, which encodes the serine/threonine protein kinase CHK2, a 65-kDa protein consisting of 543 amino acids, ubiquitously expressed in normal cells and tissues." (PMID 38367672, 2024). "Since the mutational landscape of a tumor reflects the processes that have operated on its development, the aim of this study was to uncover the somatic genomic landscape of CHEK2-associated BC." (PMID 37161532, 2023). "VHL is a tumour suppressor gene, and we postulate that the cause of the abnormal severity in the course of his disease, is an additional mutation in CHEK2, another tumour suppressor gene." (PMID 37843608, 2023). "In the current study, we have sequenced the primary tumor and normal genomes of 20 CHEK2 c.1100delC mutation carriers as well as their tumor transcriptomes." (PMID 37161532, 2023). "CHEK2 (checkpoint kinase 2) is a tumor-suppressor gene located at chromosome 22q12.1 encoding checkpoint kinase CHK2 involved in the DNA damage response." (PMID 38139220, 2023). "To understand the phenotype of T cells and tumor cells associated with low and high CHEK2 expression in tumor cells, we interrogated the single-cell RNA sequencing (scRNA-seq) data of 28 GBM patients." (PMID 36949040, 2023).
tumor (continued). "CHEK2 encodes a kinase that functions as a tumor suppressor, which is activated in cells under circumstances of DNA damage and other cellular damage." (PMID 36980535, 2023). "The proportion of variants that were present on both tumor and germline testing varied widely by gene, with the highest proportion found in CHEK2 variants (85.7%, N = 6) and the lowest proportion found in RAD51C variants (0%, N = 0)." (PMID 35962742, 2023). "Next, we analyzed the gene expression pattern of T cells associated with low and high CHEK2 expressing tumor cells." (PMID 36949040, 2023). "Contrarily, a pathogenic CHEK2 variant was detected in a patient with a GI-negative tumor, while a patient’s tumor with an inconclusive GI status harbored a likely pathogenic FANCL variant and a splice variant in ATM." (PMID 38067228, 2023). "The patient consented for clinical paired tumor/normal exome sequencing, which revealed a germline heterozygous CHEK2 c.1100delC (p.Thr367fs) frameshift variant." (PMID 36980535, 2023). "Correspondingly, the T-cell compartment associated with the low CHEK2 expressing tumor cells showed GO term enrichment for “T-cell-mediated cytotoxicity pathway” as compared to the T cells from high CHEK2 expressing tumor cells (p = 0.042)." (PMID 36949040, 2023). "Loss of heterogeneity (LOH) analysis of the tumours found that the wild type allele of the CHEK2 gene was lost for both of the patients." (PMID 35039564, 2022). "Cases of two sisters carrying a germline CHEK2 variant are highlighted whereby possible other genetic drivers were discovered on tumor analysis." (PMID 36440216, 2022). "CHEK2 is a tumor suppressor gene that encodes protein Chk2 (checkpoint kinase 2), a serine/threonine kinase." (PMID 35806485, 2022). "Since this tumor also carried a germline CHEK2 mutation (c.1100delC; p.Thr367fs) with LOH, it is more likely that this CHEK2 mutation has driven tumorigenesis." (PMID 35662281, 2022). "The ATM and CHEK2 genes encode proteins that act as tumor suppressors and are involved in the DNA damage response following generation of DNA double-strand breaks (DSBs)." (PMID 33919281, 2021). "The observations imply that tumour features should be taken into account when searching for candidate variants in CHEK2:c.del1100C carriers." (PMID 34285278, 2021). "CHEK2 is a tumor suppressor gene that encodes a serine/threonine kinase, the CHK2, that is involved in multiple cellular pathways such as DNA repair, cell cycle and apoptosis." (PMID 35127508, 2021). "The second gene, CHEK2 (Checkpoint kinase 2), is a tumour suppressor gene encoding a serine/threonine-protein kinase involved in DNA repair, cell cycle arrest and apoptosis." (PMID 33318493, 2020). "Our results clearly demonstrate that c.349A>G in the CHEK2 tumour-suppressor gene is a founder variant significantly associated with an increased risk of PrCa, suggesting its potential usefulness for cost-effective targeted genetic screening in PrCa families." (PMID 33158149, 2020). "Our results provide evidence that the c.349A>G variant in the CHEK2 tumour-suppressor gene is significantly associated with increased risk of PrCa." (PMID 33158149, 2020). "CHEK2 is a tumour suppressor gene that encodes a serine threonine kinase involved in pathways such as DNA repair, cell cycle arrest, mitosis, and apoptosis." (PMID 33158149, 2020).
tumor (continued). "Checkpoint kinase 2 (CHEK2) encodes a serine threonine kinase involved in DNA repair that serves as a cell cycle checkpoint regulator and tumor suppressor gene." (PMID 31379942, 2019). "Checkpoint kinase 2 (CHEK2) is a tumor suppressor gene that encodes the serine/threonine protein kinase CHK2, a key regulator of the cell cycle that also influences apoptosis and cell aging." (PMID 31703344, 2019). "Both the ATM and CHEK2 genes showed significantly higher mutation rates in patients with non‐TNBC versus patients with a TNBC tumor phenotype (ATM: 1.7% vs. 0.4%; P = .026; CHEK2: 3.3% vs. 0.8%, P = .002)." (PMID 29522266, 2018). "The c.157T>A (p.Ser53Thr) variant of the CHEK2 gene was homozygous in the tumour that showed CN neutral LOH in the corresponding chromosomal region." (PMID 30344923, 2018). "Checkpoint kinase 2 (encoded by CHEK2) is a putative tumour suppressor that prevents mitotic progression by inhibiting Cdc25C34." (PMID 28383032, 2017). "Predicted pathogenic germline mutations in BRCA1 and BRCA2 were identified in 1.36% and 1.64% of the cohort, respectively, and 2.22% of tumours harboured pathogenic CHEK2 germline mutations." (PMID 27161491, 2016). "In general, there was a statistically significant and ~10-fold decrease in the relative size of all BLM- and CHEK2-deficient tumor spheres treated with 2ME2, ATTM and LCS-1 relative to controls." (PMID 26318585, 2015). "Collectively, these data indicate that 2ME2, ATTM, and LCS-1 treatments decrease the total number of BLM- and CHEK2-deficient colonies, and also the sizes of 3D tumor spheres, suggesting each is a strong lead candidate therapeutic compound." (PMID 26318585, 2015). "Tumor cells that express mutated CHEK2 347 exhibited a 2-to 4-fold increase in apoptosis upon treatment with adrimycin." (PMID 25884806, 2015). "For this reason, further studies are required in order to investigate the mechanisms by which rare mutations in CHEK2 participate in tumour development." (PMID 24986639, 2014). "The genomic aberrations as well as activated or silenced genes and pathways characteristic for CHEK2 1100delC mutation-carrier tumors are good candidates for CHEK2 1100delC-related tumor-progression drivers to be investigated further." (PMID 21542898, 2011). "The CHEK2 gene (cell cycle checkpoint kinase 2) is a multiorgan tumour susceptibility gene involved in the maintenance of genomic stability." (PMID 21569354, 2011). "Twenty-eight genes located on these regions showed differential expression between CHEK2 1100delC and other tumors, nominating them as candidates for CHEK2 1100delC-associated tumor-progression drivers." (PMID 21542898, 2011). "Tumors from patients carrying CHEK2 mutation 1100delC show reduced CHEK2 protein activity that can partly be explained by the loss of the wild-type allele in tumor cells." (PMID 21542898, 2011). "CHEK2 variants, though of uncertain clinical significance, may play a role in multi-tumor predisposition." (PMID 40688847, 2025). "CHEK2 encodes a checkpoint kinase involved in DNA damage repair and tumor suppression." (PMID 40688847, 2025). "Thus, BRCA1/2 mutations, along with mutations in other mutator genes like ATM and CHEK2, have been exploited as tumor-agnostic markers, but in a unique application." (PMID 38920700, 2024).
tumor (continued). "Moreover, CHK2 expression was increased in tumor tissues, when compared to normal tissues, independently of the presence of CHEK2 germline variants." (PMID 38367672, 2024). "Therefore, future studies should evaluate for loss of CHEK2 heterozygosity in DFSP to further assess the role of this gene in tumor formation." (PMID 39669616, 2024). "In addition, a complete genetic analysis of the tumour revealed not only the presence of CHEK2 and VHL mutations, but also the presence of deletions in exon 1 of BRAF-1 and PTEN11, genes involved in tumour development by LOF." (PMID 37843608, 2023). "Following the clinical-genetic finding, the family has been referred to familiar oncology, to study the possible benefit derived from CHEK2 mutation–targeted therapy, which could stop the continuous triggering of tumour growth." (PMID 37843608, 2023). "In both cases the presence of tumours correlated to the finding of the CHEK2 mutation." (PMID 37843608, 2023). "CHEK2 is a tumor suppressor gene that encodes a serine/threonine kinase, Chk2." (PMID 38476463, 2023). "We aim to identify in the study population the prevalence of mutations in the CHEK2 gene in diagnosed BC patients, evaluate the phenotypic characteristics of the tumor and family history, and predict the deleteriousness of the variants of uncertain significance (VUS)." (PMID 38476463, 2023). "The immune responsiveness upon Chek2 inhibition/depletion shows association with enhanced antigen presentation and increased type I interferon response manifested by low Chek2 expressing tumor cells in preclinical models and in human GBM scRNA-seq datasets." (PMID 36949040, 2023). "In addition to CHEK2 mutation found in the tumour and inherited through the germ line, 2 more somatic mutations were detected only in the tumour sample." (PMID 37843608, 2023). "In addition, the patient’s tumor had mutations in genes that are associated with genetic instability, including a CHEK2 mutation and VUSs in MSH3, and MUTYH." (PMID 37202426, 2023). "Thus, CHEK2 expression in tumor cells was associated with consistent differences in the phenotype of T cells in GBM." (PMID 36949040, 2023). "In the current study, we analyzed the prevalence of 21 recurrent germline mutations in BRCA1, BRCA2, RAD51C, PALB2, and CHEK2 genes among Polish patients with BOTs and decided to determine whether are associated with the risk of developing this tumor." (PMID 35313928, 2022). "A CHEK2 S5fs∗ mutation was detected in the tumor (allele frequency [AF]: 42%)." (PMID 36061833, 2022). "Similarly to the role of ATM in cellular senescence, CHEK2 is a multiorgan tumor susceptibility gene involved in the induction of replication- and oncogene-triggered senescence to block hyperproliferation and subsequent tumorigenesis." (PMID 35406559, 2022). "Furthermore, we performed next-generation sequencing (NGS) of the patient's resected tumor tissue and peripheral blood and identified a novel CHEK2 p.H371Y germline mutation." (PMID 34716641, 2021). "The CSig3(+) ATM-BAL tumor also had a CHEK2 truncating kinase domain mutation." (PMID 34877933, 2021). "However, the most important finding is that all three patients with CHEK2 mutation developed second neoplasms." (PMID 29682443, 2018). "For patient 2, mutations in PIK3CA and CHEK2 were identified in all tumour regions and may be potential therapeutic targets (drugs are still being tested in clinical trials)." (PMID 28916750, 2017). "However, it is difficult to demonstrate that CHEK2 acts as a tumor-suppressor gene (i.e., functioning through somatic loss or inactivation of the wild-type allele) because of its low risk ratio and low allele frequency." (PMID 27900359, 2016). "Finally, we show that drug treatments significantly decrease the number and size of BLM- and CHEK2-deficient cells in 2D colony and 3D tumor spheroid formation assays, respectively." (PMID 26318585, 2015).